VPS37C (VPS37C subunit of ESCRT-I)
Description:
Component of the ESCRT-I complex, a regulator of vesicular trafficking process. Required for the sorting of endocytic ubiquitinated cargos into multivesicular bodies. May be involved in cell growth and differentiation.
Synonyms: FLJ20847
Tractability: Antibody: UniProt places it where antibodies can reach, with high confidence. PROTAC: ubiquitination databases record sites on it; its protein half-life has been measured.
Gene: Protein-coding gene on chromosome 11 (61,130,257 to 61,167,355, reverse strand). Ensembl gene ENSG00000167987.
Subcellular location: Late endosome membrane
Subcellular location (Human Protein Atlas): Nucleoplasm; Vesicles; Golgi apparatus; Primary cilium
Pathways (Reactome):
Disease: Budding and maturation of HIV virion; HCMV Late Events; Membrane binding and targetting of GAG proteins
Autophagy: Late endosomal microautophagy
Vesicle-mediated transport: Endosomal Sorting Complex Required For Transport (ESCRT)
Gene Ontology:
Molecular function: calcium-dependent protein binding; protein binding
Biological process: macroautophagy; membrane fission; multivesicular body assembly; protein targeting to membrane; protein targeting to vacuole; protein transport to vacuole involved in ubiquitin-dependent protein catabolic process via the multivesicular body sorting pathway; ubiquitin-dependent protein catabolic process via the multivesicular body sorting pathway; viral budding via host ESCRT complex
Cellular component: ESCRT I complex; extracellular exosome; nucleoplasm; endosome membrane; late endosome membrane
Genetic constraint (gnomAD): Loss-of-function variants: 9 observed, 16.31 expected, observed/expected ratio (o/e) 0.55, 90% interval 0.33 to 0.96. The upper end of that interval is the gene's LOEUF score, 0.96, which puts it in group 4 of 6, group 1 being the genes least tolerant of losing a copy. Missense variants: 479 observed, 398.39 expected, observed/expected ratio (o/e) 1.2, 90% interval 1.12 to 1.3. Synonymous variants: 207 observed, 176.34 expected, observed/expected ratio (o/e) 1.17, 90% interval 1.05 to 1.32.
Homologues: Orthologues: chimpanzee VPS37C (98% identical), macaque VPS37C (95% identical), rabbit VPS37C (88% identical), dog VPS37C (85% identical), pig VPS37C (83% identical), mouse Vps37c (82% identical), rat Vps37c (81% identical), guinea pig VPS37C (76% identical), zebrafish vps37c (32% identical), Drosophila melanogaster Vps37B (18% identical). Paralogues in human: VPS37B (32% identical), VPS37D (23% identical), VPS37A (14% identical).
Diseases named in the same sentence as VPS37C in open-access papers:
VPS37C is named in the same sentence as 5 diseases in open-access papers, as found by Europe PMC text mining. Sharing a sentence is not in itself a finding about the gene and the disease. The quoted sentences say what the papers report.
Kawasaki disease (1 paper, 2025). A rare inflammatory disease characterized by an acute febrile, systemic, self-limiting, medium-vessel vasculitis primarily affecting children. "Similarly, VPS37C is included in the transcriptomic signature that differentiates multisystem inflammatory syndrome in children (occurring weeks after SARS-CoV-2 infection) from Kawasaki disease and other infections." (PMID 41009814, 2025).
bacterial infections (1 paper, 2023). "Variable selection using FS-PLS identified 4 genes distinguishing MIS-C from KD, viral and bacterial infections: HSPB1 Associated Protein 1 (HSPBAP1), Vacuolar Protein Sorting-Associated Protein 37C (VPS37C), Transforming Growth Factor Beta 1 (TGFB1) and MX Dynamin Like GTPase 2 (MX2)." (PMID 37255317, 2023).
cancer (1 paper, 2025). A tumor composed of atypical neoplastic, often pleomorphic cells that invade other tissues. "Some genes exhibited positive regulation in particular cancer types, including VPS37C in DLBC and CHMP3 and VPS37B in TGCT, which were positively correlated with immune cell enrichment." (PMID 40230849, 2025).
infection (1 paper, 2025). The state of being infected such as from the introduction of a foreign agent such as serum, vaccine, antigenic substance or organism. "The involvement of CD5 and VPS37C suggests that long COVID may be influenced by sustained immune dysregulation after the initial infection." (PMID 41009814, 2025).
VPS37C also shares sentences with these, for which no sentence is quoted: breast carcinoma (2 papers).